KLHL24 (kelch like family member 24)
Description:
Necessary to maintain the balance between intermediate filament stability and degradation, a process that is essential for skin integrity. As part of the BCR(KLHL24) E3 ubiquitin ligase complex, mediates ubiquitination of KRT14 and controls its levels during keratinocytes differentiation. Specifically reduces kainate receptor-mediated currents in hippocampal neurons, most probably by modulating channel properties (By similarity). Has a crucial role in cardiac development and function.
Synonyms: KRIP6; DRE1; FLJ20059; CMH29; EBS6; EBSSH
Tractability: Small molecule: it belongs to a druggable protein family. PROTAC: UniProt records ubiquitination sites on it; ubiquitination databases record sites on it.
Gene: Protein-coding gene on chromosome 3 (183,635,602 to 183,684,519, forward strand). Ensembl gene ENSG00000114796.
Subcellular location: Perikaryon; Cell projection, axon; Cytoplasm; Cell junction, desmosome; Cell junction, adherens junction
Gene Ontology:
Molecular function: protein binding; ubiquitin-like ligase-substrate adaptor activity
Biological process: intermediate filament organization; protein autoubiquitination; protein ubiquitination; proteasome-mediated ubiquitin-dependent protein catabolic process
Cellular component: adherens junction; Cul3-RING ubiquitin ligase complex; cytoplasm; desmosome; axon; perikaryon
Genetic constraint (gnomAD): Loss-of-function variants: 15 observed, 35.57 expected, observed/expected ratio (o/e) 0.42, 90% interval 0.28 to 0.65. The upper end of that interval is the gene's LOEUF score, 0.65, which puts it in group 2 of 6, group 1 being the genes least tolerant of losing a copy. Missense variants: 402 observed, 614.93 expected, observed/expected ratio (o/e) 0.65, 90% interval 0.6 to 0.71. Synonymous variants: 174 observed, 212.5 expected, observed/expected ratio (o/e) 0.82, 90% interval 0.72 to 0.93.
Gene-disease validity (ClinGen):
ClinGen rates the evidence that KLHL24 causes each of these diseases.
hypertrophic cardiomyopathy (autosomal recessive): Moderate. A condition in which the myocardium is hypertrophied without an obvious cause.
Homologues: Orthologues: chimpanzee KLHL24 (100% identical), dog KLHL24 (99% identical), pig KLHL24 (99% identical), rabbit KLHL24 (99% identical), mouse Klhl24 (99% identical), rat Klhl24 (99% identical), guinea pig KLHL24 (99% identical), tropical clawed frog klhl24 (91% identical), zebrafish klhl24b (85% identical), zebrafish klhl24a (78% identical). Paralogues in human: KLHL6 (44% identical), KLHL35 (43% identical), KLHL29 (34% identical), KLHL2 (33% identical), KLHL20 (33% identical), KLHL12 (32% identical), KLHL3 (32% identical), KLHL21 (30% identical), KLHL38 (30% identical), KLHL5 (30% identical), KLHL17 (30% identical), KLHL28 (30% identical), and 42 more.
Diseases named in the same sentence as KLHL24 in open-access papers:
KLHL24 is named in the same sentence as 29 diseases in open-access papers, as found by Europe PMC text mining. Sharing a sentence is not in itself a finding about the gene and the disease. The quoted sentences say what the papers report.
cardiomyopathy (5 papers, 2022 to 2026). A disease of the heart muscle or myocardium proper. "Our findings add to the mutational spectrum of recessive cardiomyopathies, supporting inclusion of KLHL24, NRAP and RBCK1 as disease-causing genes." (PMID 36672924, 2023). "Epidermolysis bullosa simplex (EBS) with cardiomyopathy (EBS-KLHL24) is an EBS subtype caused by dominantly inherited, gain-of-function mutations in the gene encoding for the ubiquitin-ligase KLHL24, which addresses specific proteins to proteasomal degradation." (PMID 34740256, 2022). "This case expands the genetic spectrum of HCM and highlights the importance of genetic testing and family screening for KLHL24-related cardiomyopathies." (PMID 42158087, 2026). "Pathogenic variants in Kelch-like family member 24 (KLHL24; NM_017644.3) were recently identified as a new cause for skin fragility and cardiomyopathy." (PMID 37191012, 2023).
hypertrophic cardiomyopathy (4 papers, 2022 to 2026). "Conversely, loss of function mutations in KLHL24 are associated with increased desmin expression in cardiac and skeletal muscle tissues of patients affected with hypertrophic cardiomyopathy." (PMID 34740256, 2022). "On the other hand, loss-of-function mutations lying within two different KLHL24 functional domains have been recently shown to cause a recessively inherited form of hypertrophic cardiomyopathy, characterized by polyglucan, glycogen and desmin accumulation." (PMID 34740256, 2022). "KLHL24 inactivation is associated with hypertrophic cardiomyopathy." (PMID 38898455, 2024). "Moreover, mutations in KLHL24 (Kelch like family member 24) were found to cause hypertrophic cardiomyopathy, a common inherited cardiovascular disorder, and silencing the klhl24a gene in zebrafish caused defects in cardiac function." (PMID 35327608, 2022). "Phenotypic and pathological findings in EBS-KLHL24 and KLHL24-dependent hypertrophic cardiomyopathy resulted in the identification of intermediate filaments (IFs) as candidate substrates of KLHL24-mediated degradation in the skin and heart, respectively." (PMID 34740256, 2022).
acute myeloid leukemia (3 papers, 2021 to 2023). Acute myeloid leukemia (AML) is a group of neoplasms arising from precursor cells committed to the myeloid cell-line differentiation. "KLHL24 found in acute myeloid leukemia as an autophagy-related gene to inform prognostic assessment." (PMID 37138885, 2023). "Indeed, very recently Klhl24 has been identified as part of an autophagy related signature in acute myeloid leukemia." (PMID 34990474, 2022). "KLHL24 has been uncovered as a prognostic predictor for acute myeloid leukemia." (PMID 34238288, 2021).
breast carcinoma (2 papers, 2017 to 2022). "In the case of Klhl24, a better probability of relapse-free survival in all breast cancer patients (RSF) and ER+ only patients (RSF ER+) was associated with higher levels of the mRNA with a p≤ 6.5X10-7." (PMID 34990474, 2022). "Our data suggests that Klhl24 mRNA can be used to monitor autophagy in patients undergoing breast cancer therapy." (PMID 34990474, 2022). "High levels of Klhl24, Hbp1, Crebrf, Ypel2, CD22 and Ypel3 were correlated with better outcomes, whereas lower levels of Gdf15, Cdc25a, Ddit4 and Psat1 were associated with better prognosis in breast cancer patients." (PMID 34990474, 2022). "Twenty of the 27 common genes have published data presenting that these genes were associated with breast cancer, but seven genes (DUSP10, GABRA6, GABRR1, KIF21B, KLHL24, MAP2K2, and SLC10A1) might be passenger genes or have not yet been studied regarding their pathological roles in breast cancer." (PMID 28973975, 2017).
epidermolysis bullosa (2 papers, 2021 to 2024). Epidermolysis bullosa (EB) is a group of genetic skin diseases that cause the skin to blister very easily. "People who carry a mutation in the KLHL24 gene are at risk of developing epidermolysis bullosa." (PMID 38898455, 2024).
breast tumor (1 paper, 2021). "Bockers suggested that KLHL24 associated with ESR1 could act as the upstream regulator to promote breast tumor growth." (PMID 34238288, 2021).
cardiocutaneous syndrome (1 paper, 2022). "The reported variants associated with cardiocutaneous syndrome, in genes DSP, JUP, DSC2, KLHL24, GJA1, are classified by interpretation guidelines from the American College of Medical Genetics and Genomics." (PMID 36142674, 2022).
dilated cardiomyopathy (1 paper, 2022). Cardiomyopathy which is characterized by dilation and contractile dysfunction of the left and right ventricles. "In addition, EBS-KLHL24 patients develop in the early adulthood a life-threatening dilated cardiomyopathy determined by the KLHL24-mediated degradation of the intermediate filament desmin in cardiomyocytes." (PMID 34740256, 2022).
skin atrophy (1 paper, 2022). The degeneration and thinning of the epidermis and dermis. "In conclusion our findings identify foetal keratins as novel KLHL24 targets which could underlie congenital skin defects and also indirectly contribute to the injury-driven postnatal skin atrophy in EBS-KLHL24." (PMID 34740256, 2022).
skin fragility (1 paper, 2022). "As EBS-KLHL24 patients are borne with congenital diffuse skin defects and their skin fragility rapidly ameliorates after birth, we hypothesized that one or more keratins expressed by keratinocytes during foetal epidermal development could represent additional KLHL24 targets." (PMID 34740256, 2022).
tumor (2 papers, 2021 to 2022). "At the same time, there were significant differences in the expression of these genes in tumor samples and normal samples, with the exception of TP63, KLHL24, and LAMP2, which were all downregulated in tumors." (PMID 36147441, 2022). "Among these ten genes, the expression levels of SETD1B, ACSF2, MUC1, KLHL24, PML, MT1G, and GPT2 were higher in tumor tissues than those in normal tissues, while HIC1, AKR1C1, and LOC390705 were lower expressed in tumor tissues." (PMID 35071242, 2021).
cancer (1 paper, 2022). A tumor composed of atypical neoplastic, often pleomorphic cells that invade other tissues. "Indeed, Klhl24 is a validated target of an established autophagy related microRNA (miR 124), and one of the mRNAs modulated by autophagy-inducing stimuli like rapamycin and serum starvation in cancer cells." (PMID 34990474, 2022).
cardiac disease (1 paper, 2022). "A substantial number of genetic variants in the genes DSP, JUP, DSC2, KLHL24 and GJA1 have been reported to underly skin and/or cardiac disease." (PMID 36142674, 2022).
infection (1 paper, 2021). The state of being infected such as from the introduction of a foreign agent such as serum, vaccine, antigenic substance or organism. "Interestingly, in this present study, whereas PCPEC displayed a strong inflammatory response to infection, genes attributed to hypoxia were found to play a more prominent role during infection in HIBCPP cells (including ZFP36L1, MXI1, KLHL24, PNRC1, CDKN1C, and DUSP2)." (PMID 33763387, 2021).
KLHL24 also shares sentences with these, for which no sentence is quoted: epidermolysis bullosa simplex (4 papers); Aicardi-Goutieres syndrome (1); aplasia cutis congenita (1); B cell lymphomas (1); bladder cancer (1); cardiovascular disorder (1); congenital disorder of glycosylation type Im (1); congenital heart disease (1); congenital nemaline myopathies (1); distal myopathy (1); gastric cancer (1); infertile (1); Intellectual disability (1); nephrotic syndrome (1); viral infection (1).